TNF (tumor necrosis factor)
Diseases named in the same sentence as TNF in open-access papers (continued):
Sharing a sentence is not in itself a finding about the gene and the disease.
dengue (continued). "Proinflammatory cytokines such as TNFα, IFNγ, and IL-6 have been associated with severe secondary dengue disease in several studies." (PMID 22816004, 2012). "Our data suggest that serum IL-10, TNFα and TGFβ differentially associate with dengue disease severity." (PMID 23209731, 2012). "The inability to downregulate innate cytokines, particularly TNF‐α, IL‐6, and IP‐10, during the late phase of illness has been associated with delayed resolution of serum inflammatory mediators in patients with severe dengue." (PMID 41488232, 2026). "In severe human dengue, Kupffer cell-associated TNF-α has been implicated in disease pathogenesis." (PMID 41472288, 2025). "The final analysis revealed that multiple polymorphisms in immune system genes were early markers of the progression of dengue in Latin Americans and found that polymorphisms of the TNF-alpha gene may have a critical role in dengue pathogenesis." (PMID 38055376, 2023). "Evidence suggests that cytotoxic T cells may be sufficient to cause the occurrence of severe signs of dengue, in addition to stimulating the expression of inflammatory cytokines, such as Tumor Necrosis Factor (TNF)." (PMID 36558877, 2022). "Interestingly, sensing of prM-DENV2 triggered the production of TNF-α, IL-1β, and IL-6 cytokines which are usually associated with EC activation and damage during severe dengue." (PMID 36240261, 2022). "Proinflammatory cytokines such as TNF-α are positively associated with severe dengue disease." (PMID 33869639, 2021). "Indeed, antibody enhanced dengue disease in marmosets lead to CNS injury and was associated with intense TNF-α immunostaining in brain samples." (PMID 30568659, 2018). "Only 3 studies assessed both TNF-α-308 G>A and TNF-α 238 G>A in the risk of severe dengue." (PMID 30300401, 2018). "Likewise, significant systemic levels of TNF-α have been associated with severe secondary infections with dengue." (PMID 29976871, 2018). "In addition to TNF, other monocyte-secreted factors can prime or trigger endothelial cell permeability leading to vascular leakage, a major hallmark of severe dengue disease." (PMID 30409217, 2018). "Moreover, human genetic studies of cytokine gene polymorphisms highlight a strong role for TNF in the severity of dengue disease." (PMID 30409217, 2018). "Increased CXCL10 and TNFα are associated with increased disease severity in Dengue patients." (PMID 30112159, 2018). "Hence, it is clear that TNFα is a key pathogenic cytokine responsible for the different disease manifestations such as liver damage and vascular leakage in various murine dengue models." (PMID 27007501, 2016). "TNF-α has been associated with hemorrhagic manifestations of dengue." (PMID 27301555, 2016). "In addition to inherent antipyretic activity in Wistar rats, it possessed the ability to down-regulate the production of TNF-α, a cytokine implicated in severe dengue disease." (PMID 26709822, 2015). "On the other hand, as direct invasion of muscle by virus has not been demonstrated consistently, a more likely cause of myositis and rhabdomyolysis in dengue fever could be the release of myotoxic cytokines, particularly the tumor necrosis factor." (PMID 23889764, 2013). "Furthermore, TNF-α has been reported to induce hemorrhage by causing endothelial cell death, which is associated with increased endothelial cell permeability, in an experimental dengue hemorrhage mouse model." (PMID 26199460, 2015). "On the other hand, it has been demonstrated that EVs released by virus-activated platelets contain IL-1β and TNF-α, which together contribute to inflammation and play a central role in endothelial activation and plasma leakage during severe dengue." (PMID 40573398, 2025). "In severe dengue, the immune system’s response produces cytokines such as interleukin 6 (IL-6) and tumor necrosis factor alpha (TNF-α), which increase BBB permeability and contribute to vasogenic edema." (PMID 40600037, 2025).
dengue (continued). "In contrast TNF, a cytokine with an established role in vascular leak, had a potent effect when used at a concentration seen in severe dengue disease." (PMID 41218088, 2025). "One of the main mechanisms involved in the multiorgan failure observed in patients with severe dengue is the excessive production of TNF-α, which in high concentrations favors plasma extravasation." (PMID 40299497, 2025). "Although neutropenia is common in dengue, there is clear evidence of neutrophil activation during dengue infection, as evidenced by elevated levels of IL-8 and TNF alpha." (PMID 39066252, 2024). "The elevated level of IgG2a in a mouse model is considered significant for dengue vaccine efficacy in association with the Th1 subset of CD4+ T cells secreting IFN-γ and TNF." (PMID 38250905, 2024). "In previous mouse models for severe dengue, blockade of TNF-α protected mice from lethal infection, suggesting a central role in lethality." (PMID 38550855, 2024). "The damage to muscle cells brought on by the release of cytokines, particularly TNF and interferon alpha, which are sparked by the DENV, is thought to be the cause of dengue-related rhabdomyolysis." (PMID 38313931, 2024). "Dengue disease is characterized by an inflammatory-mediated immunopathology, with elevated levels of circulating factors including TNF-α and IL-6." (PMID 38054722, 2024). "The in vivo study from our group highlighted that Sinococuline treatment in dengue-infected mice reduced the viral loads in the vital organs as well as tissue proinflammatory cytokine levels like TNF-α and IL-6." (PMID 39770732, 2024). "Several studies have found that IL-6, IL-17A, IFN-α, IL-1β, IL-10, and TNF-α play different roles in dengue disease, but we didn't know which factor play key roles or even correlated with IL-37b and other factors." (PMID 37024713, 2023). "Resistin is mainly produced by monocytes, macrophages and other leucocytes and its production is shown to be stimulated by lipopolysaccharide (LPS) and cytokines such as IL-6, TNFα and IL-1β, which are all shown to be elevated during early illness in dengue." (PMID 37676889, 2023). "Maintaining the cell viability of Dengue-infected cells, decrease in the TNF α and increase in the interferon γ production in Dengue-infected cells." (PMID 38027169, 2023). "In another published study performed on a mouse model, recombinant dengue NS1 produced in human embryonic kidney (HEK) 293 cells or in S2 cells was able to stimulate TNF-α and IL-6 three days after intravenous administration." (PMID 36674524, 2023). "Many studies showed that high levels of interferon-alpha (IFN-α), IL-8, IL-6, tumor necrosis factor-alpha (TNF-α), IL-10, and IFN-γ are associated with different stages of severe dengue disease." (PMID 36770606, 2023). "The pro-inflammatory profile was mainly characterized by the expression of IFN-γ and TNF-α, two classic cytokines involved in dengue virus infection in children and in the progression of its severity." (PMID 36558877, 2022). "Altogether, these results indicate that TLR2/TLR6/CD14- mediated sensing of immature dengue particles induces the production of TNF-α and IL-1β by monocytes." (PMID 36240261, 2022). "A study in dengue-infected mice showed that anti- TNF antibody is able to reduce dengue-infected mice mortality, with gradual recovery of platelet and erythrocyte counts." (PMID 35864519, 2022). "A low expression of moesin, alterations to actin stress fibers, and a dot-like structural formation of vinculin are responsible for the cellular permeability changes of human ECs during dengue virus infection and TNF-α induction." (PMID 34696472, 2021). "Another study showed that a high level of TNF-α was strongly correlated with the severity of dengue patients." (PMID 34696472, 2021). "This work studied the status of pentraxin (CRP/SAP) protein, ferritin, TNF-α and IL-1β levels in Dengue patients of different pathophysiological manifestations." (PMID 33436908, 2021).
dengue (continued). "Cytokines including TNF- α, IFN- γ, IL-1β, IL-2, IL-6 and IL-10 have been linked to the pathogenesis of other viral hemorrhagic diseases, such as dengue, and Ebola." (PMID 34793450, 2021). "Statistically significant increased CRP, SAP, ferritin, TNF-α and IL-1β titres were correlated in patients with severe clinical manifestations as compared to mild disease forms of dengue." (PMID 33436908, 2021). "In case of dengue, RNAi approaches have obtained promising results by targeting TNF-α in cell culture and mice." (PMID 33816326, 2021). "A study of a mouse model of dengue hemorrhage implied that TNF-α induces hemorrhage, resulting in endothelial cell death." (PMID 34394108, 2021). "TNF-α is highly elevated in dengue patient, and it is likely to result in increased vascular permeability." (PMID 34696472, 2021). "Higher levels of TNF-α and IL-1β were observed in secondary dengue infections compared to primary dengue cases which was statistically significant (p < 0.0001)." (PMID 33436908, 2021). "Another study showed that B cells isolated from pediatric dengue patients spontaneously secreted TNF-α, IL-6, and IL-10, and supernatants from cultures of purified B cells induced activation of allogeneic T cells." (PMID 34293057, 2021). "Tumor necrosis factor α (TNFα) induces apoptosis of the endothelial cells and shows promise as a biomarker of severe dengue." (PMID 33364116, 2020). "Doxycycline was the more effective tetracycline in the reduction of IL-6 and TNF-α in patients with dengue fever." (PMID 33142770, 2020). "Many Dengue studies have demonstrated that antiviral NK cells cooperate with IFNs and TNF-α to eliminate virus from DENV-infected DCs and DENV-infected mice." (PMID 33072626, 2020). "Higher concentrations of cytokines such as IFN-γ, TNF-α and IL-10 were observed in the sera of patients with severe dengue in Cuba, India and Vietnam." (PMID 32751561, 2020). "C57BL/6 mice infected with DENV-1 strain Mochizuki presented some signs of dengue disease such as thrombocytopenia, hemorrhage, liver damage, and increase production of IFNγ and tumor necrosis factor alpha (TNFα) cytokines." (PMID 30625992, 2019). "For instance, NS3-specific CD8+ T cells from donors with severe dengue had a higher production of tumor necrosis factor (TNF) vs. IFNγ compared with children with mild dengue." (PMID 31244855, 2019). "High levels of circulating proinflammatory cytokines such as IL-1β or tumor necrosis factor α (TNF-α) also correlates with severe dengue fever in DENV-infected patients." (PMID 31531178, 2019). "In support of this, greater numbers of dengue specific CD8s producing TNFα, IFNγ, and IL-2 prior to heterotypic infection was associated with an asymptomatic infection." (PMID 31816907, 2019). "Circulating TNF levels are altered in severely afflicted dengue patients and TNF is a crucial factor in DENV-induced hemorrhage in a mouse model." (PMID 30409217, 2018). "Infected mice by dengue showing increased TNF-a, IFN-g and IL-6 levels, which were recognized as triggers for DENV were also reported." (PMID 29301573, 2018). "Further, based on biomarker network analysis, two relevant strong axes during early stages of dengue fever were identified—a protective axis composed of TNF-α/lymphocytes/platelets, and a pathological axis IL-2/IL-6/monocyte/prothrombin time/viremia." (PMID 30568659, 2018). "TNFα secretion levels were increased in serum of individual Dengue groups; DF (P <0.001), DWS (P=0.005) and SD (P=0.004) as compared with healthy controls." (PMID 30112159, 2018). "Dengue virus-induced inflammatory cytokines such as TNF-α, IL-6, and IL-8 are critical in the pathogenesis of dengue fever and dengue hemorrhagic fever." (PMID 30186771, 2018). "We investigated the association of the cytokines TNFα, IL-6 and CXCL10 in patients with differing Dengue disease severity as compared with healthy controls." (PMID 30112159, 2018).
dengue (continued). "In this study, increased levels of TNFα observed in Dengue patients as compared with healthy controls are in line with above findings." (PMID 30112159, 2018). "Our results show variation between IL-6 levels and increase in TNFα and CXCL10 serum levels to be associated with Dengue severity." (PMID 30112159, 2018). "Dengue virus (DENV) infection induces TNFα and IL-6 production in dengue patients, and serum TNFα is positively correlated with disease progression." (PMID 29668683, 2018). "Several of these cytokines have been identified as markers of dengue in humans, including IL-12, IL-13, IL-17A, G-CSF, IFNγ, and TNFα." (PMID 29559699, 2018). "Serum concentrations of IL-2, IL-4, IL-6, IFN-γ, TNF-α, IL-17, and IL-10 were determined in dengue patients at 6 or 7 days of fever onset and were compared with values obtained in a group of healthy controls." (PMID 28827898, 2017). "In relation to non-severity biomarkers, it was found that dengue-3 significantly induced higher levels of IL-12 and sVCAM-1, whereas dengue-1 significantly induced lower levels of TNF-α, compared to other dengue serotypes." (PMID 28929009, 2017). "TNF-α has been found in a broad concentration range in dengue patients, that is, influenced by the time of blood sampling and TNF-α's genetic polymorphisms." (PMID 28827898, 2017). "Acute serum IL-6, IL-10 and TNF-α levels were measured in 22 dengue patients (12 DF and 10 DHF patients) either on enrollment (n = 19) or 1 day (n = 3) afterwards." (PMID 28393899, 2017). "Diverse single nucleotide polymorphisms (SNPs) in genes such as HLA-I, HLA-II, TNF-α, IL-10, TGF-β1, FcγRIIa, VDR, CD209 and OAS have been associated with symptomatic dengue or considered protective against the disease, in Asian and Latin American populations." (PMID 28241052, 2017). "Inconsistencies in TNFα levels in these cytokine profiling studies of dengue patients have largely been attributed to possible differences in collection time points and discrepancies in the assessment of disease severities." (PMID 27007501, 2016). "Although the TNF-α inhibition assay was key to infer its importance in severe dengue, in practical terms, targeting TNF with antibody or receptor antagonists for treating human diseases is controversial." (PMID 28006034, 2016). "TNF-α, which is an important cytokine related to dengue pathogenesis, was detected mainly in alveolar macrophages." (PMID 28006034, 2016). "The increased levels of Hct, interleukin- (IL-) 10, and tumor necrosis factor-alpha (TNF-α) were detected in dengue fever (DF), dengue hemorrhagic fever (DHF) and dengue shock syndrome (DSS) patients as compared with other febrile illnesses (OFIs)." (PMID 25722892, 2015). "The original report of the severe dengue produced by DENV-2 D2S10 in AG129 mice demonstrated the importance of TNF-α in disease progression." (PMID 25938762, 2015). "Treg have an impact on the expression of IFN-γ, TNF-α, and IL-6 production in response to dengue antigens in vitro." (PMID 25010330, 2014). "This set of data provides a direct experimental evidence of a role for TNF-α in increased vascular permeability in an in vivo model of severe dengue." (PMID 24699622, 2014). "The relationships between in vivo dengue virus nonstructural protein 1 (NS1) levels and innate immune response parameters (TLR4 expression and TNF-α/NO production) in infected dengue patients were investigated in our work." (PMID 25580138, 2014). "Evidence that implicates immune factors in dengue severity is derived from chemical mediators, such as tumor necrosis factors (TNF), interleukin-1 (IL1), IL2, IL6, platelet-activating factor (PAF), complement components C3a and C5a, and histamine." (PMID 24727912, 2014). "Molecules such as IFN gamma and TNF alpha appear to be markers for the different degrees of dengue disease or the dengue prognosis." (PMID 23978258, 2013). "In dengue patients, elevated TNF-α levels, which seems to correlate with disease severity, are observed." (PMID 24302878, 2013).
dengue (continued). "Dengue virus infection has been shown to increase the production of the tumor necrosis factor in humans." (PMID 23889764, 2013). "C57BL/6 mice have been established as a dengue hemorrhage model and found that TNF-α is a very important cytokine that induces endothelial damage and hemorrhage." (PMID 22666132, 2012). "In summary, we have found that C57BL/6 mice infected intraperitoneally with DENV-1 presented some signs of dengue disease such as thrombocytopenia, hemorrhage, liver damage, and increase production of IFNγ and TNFα cytokines." (PMID 22666132, 2012). "In our study, we have found that immunocompetent C57BL/6 mice infected intraperitoneally with DENV-1 presented some signs of dengue disease such as thrombocytopenia, spleen hemorrhage, liver damage, and increase in production of IFNγ and TNFα cytokines." (PMID 22666132, 2012). "High IL-10 and TNF-α serum values were also found in patients with severe course of dengue hemorrhagic fever and Argentine hemorrhagic fever, which have similar clinical presentations to HFRS." (PMID 21605369, 2011). "It is well known that higher concentrations of TNF-α correlate with severe dengue disease in vivo and high viral titers in vitro and in vivo." (PMID 21388530, 2011). "The circulating levels of four cytokines, IFN-γ, TNF-α, IL-6 and IL-8 were assessed in the 221 confirmed dengue cases." (PMID 20090849, 2010). "In comparison to those with uncomplicated dengue fever, patients with DHF/DSS have higher plasma levels of inflammatory cytokines IL-6, IL-8, and TNFα, and both IL-8 and TNFα levels are independent correlates of dengue disease severity." (PMID 21206915, 2010). "Cytokines that are undetectable in the blood of healthy individuals are elevated in dengue-infected patients, such as IL-1β, IL-2, IL-6, IL-8, IL-10, IL-13, IL-18, IFNγ, TNFα, and MCP1." (PMID 21206915, 2010). "We assessed the levels of inflammatory mediators- IFN-γ, TNF-α, IL-6 and IL-8 in well characterized dengue patients in context to their clinical presentation combined with laboratory findings, the day of illness and the immune status of the patient." (PMID 20090849, 2010). "This process may contribute to the expression of TNF-α, NF-κB, and IFN-β, factors associated with neuroinflammation—a complication observed in severe dengue cases that remains poorly understood from a pathophysiological perspective." (PMID 40573398, 2025). "Apart from that, similar to other infections, dengue virus infection in non-pregnant patients was associated with an inflammatory response, such as higher levels of IL-8, IL-6 and tumor necrosis factor (TNF)." (PMID 40272573, 2025). "Patients with severe dengue disease and those with acute Japanese encephalitis exhibited excessively high levels of proinflammatory cytokines, known as a cytokine storm, including GM-CSF, TNF-α, IL-3, IL-6, and IL-8/CXCL8." (PMID 39972499, 2025). "In addition, TNF-a was observes as one of the most prominent cytokines in the evaluation of immunoclusters in severe dengue in children." (PMID 39967674, 2025). "Therefore, more studies are required before concluding anti-TNF-α therapy for dengue-infected patients." (PMID 39745465, 2025). "While immunomodulators (such as IL-6 inhibitors or tumor necrosis factor alpha (TNF-alpha) blockers) show promise in other inflammatory conditions, their use in severe dengue remains investigational, with limited preliminary data and concern about potential hemorrhagic complications." (PMID 40385752, 2025). "In addition, some EVs released from DENV-activated platelets contain interleukin-1 (IL-1), which, when combined with tumor necrosis factor-alpha (TNF-α), can become a significant factor in dengue inflammation, plasma leakage, and endothelial activation." (PMID 39553300, 2024). "Moreover, TNF signaling, IL-17 signaling, and NF-kB signaling cascades play key roles in the progression of dengue severity." (PMID 39770732, 2024).